CCL5 (C-C motif chemokine ligand 5)
Diseases named in the same sentence as CCL5 in open-access papers (continued):
Sharing a sentence is not in itself a finding about the gene and the disease.
encephalitis (14 papers, 2010 to 2025). An acute inflammatory process affecting the brain parenchyma. "Loss of dopaminergic neurons has been reported in CCR5 deficient mice, and CCL5 promotes neuronal survival in proapoptotic conditions, and protects against certain encephalitis virus." (PMID 32324857, 2020). "Vividly increased expression of CCL5 in brains of mice with WNV-encephalitis and TBE suggests it as a main CCR5 ligand in this setting." (PMID 26906062, 2016). "Although disease progression was faster in SARS-CoV-2 infected mice, infection with both viruses resulted in neuronal infection and encephalitis with increased expression of Interferon-stimulated Irf7, Bst2, Ifi294, as well as CxCL10, CCL5, CLC2, and LILRB4, and both models were uniformly lethal." (PMID 35967447, 2022). "Significantly higher levels of CCL11 (p = 0.0107), CCL2 (p = 0.0182), CCL5 (p = 0.0171) and CXCL5 (p = 0.0049) were observed in encephalitis patients." (PMID 40517242, 2025). "According to previous studies on cerebrospinal fluid (CSF) chemokines in EV71 patients with encephalitis or meningoencephalitis (ME), CSF IL-6, IL8, CCL5 and CXCL10 concentrations were significantly higher compared to patients with febrile convulsion (FC)." (PMID 31575039, 2019). "In line with a previous study of viral encephalitis we found higher relative levels of CCL-2 and IL-6 in the CSF than serum and higher levels of CCL-5 in serum; in our study this was also found in those with immune-mediated and unknown aetiologies." (PMID 26808276, 2016). "Additionally, marked elevation of several immune markers (CCL11, CCL2, CCL5, CXCL5, and IL-12p70) in the CSF of encephalitis patients may explain the more severe course of infection and poorer outcomes observed (highest number of neurological symptoms and ICU admissions)." (PMID 40517242, 2025). "Expression of CCL3, CCL5, CCL7 and CCL19 chemokines could play a crucial role in recruitment of IFN-γ-producing CD8+ T cells into the brain, and in facilitating migration of effector macrophages for prevention of Toxoplasma encephalitis during acute stage of encephalitis." (PMID 23374751, 2013).
endothelial dysfunction (14 papers, 2009 to 2025). In vascular diseases, endothelial dysfunction is a systemic pathological state of the endothelium (the inner lining of blood vessels) and can be broadly defined as an imbalance between vasodilating and vasoconstricting substances produced by (or acting on) the endothelium. "The presence of some endothelial dysfunction in this model is consistent with the IBD-related increase in expression of the chemokine ccl5 and its receptor ccr1, which are linked to endothelial dysfunction and leukocyte transmigration into arteries." (PMID 37342800, 2023). "In the serum of patients with CSU, higher levels of VCAM1, ICAM1 and CCL5/RANTES have been found: these molecules could have the role of markers of endothelial dysfunction and be implicated in the pathogenesis of CSU." (PMID 32390768, 2020). "We further demonstrated that mesenteric arteries and aorta incubated with recombinant CCL5 exhibited endothelial dysfunction, suggesting that CCL5 might induce vascular injury by acting directly in the vasculature or by modulating the immune response." (PMID 40859641, 2025). "CCL5 secretion facilitates endothelial progenitor cell recruitment and increases NO production in endothelial cells, protecting vascular endothelium from endothelial dysfunction." (PMID 35206797, 2022). "A chemokine CCL5 (RANTES) receptor, G-protein-coupled receptor GPR75 (Gq), was identified to bind to 20-HETE leading to endothelial dysfunction." (PMID 31514409, 2019).
heart failure (14 papers, 2014 to 2025). Inability of the heart to pump blood at an adequate rate to meet tissue metabolic requirements. "Research has suggested three potential biomarker genes (ASB14, CD163, and CCL5) associated with heart failure through the traditional protein–protein interaction algorithm." (PMID 40297163, 2025). "Thus, in Cyc cells we observed higher expression of genes encoding Nppa, Ccl5, Ctgf and Ankrd1, which have been shown to be associated with heart failure in earlier studies." (PMID 25799225, 2015). "Blocking of CCL5 significantly reduced infarct size in mouse models of heart failure and was identified as a key inflammatory mediator in the EAT of patients with heart failure." (PMID 39271815, 2024). "Concentrations of MCP-1/CCL-2, EOTAXIN/CCL11 and RANTES/CCL5 were significantly higher in the saliva of heart failure subjects with both NS and HS compared to the controls, while IL-8/CXCL8 level was considerably higher only in heart failure patients with NS." (PMID 36300113, 2022). "Interestingly, CCL5 is reported as a key factor in post-infarction heart failure and in the reparative and angiogenic action of transplanted ADSC on ischemic tissue." (PMID 35784739, 2022). "Increase of CCL5 serum levels was also observed in patients with severe congestive heart failure, whereas upregulation of IL-1β exhibited a significant increase in 1-year mortality in the patients with heart failure." (PMID 34925046, 2021). "The modules related to germ cell migration and disrupted cellular calcium ion homeostasis were solely detected in heart failure arising from ISCM, with increased CXCR4, CCL5, and CXCL12." (PMID 29160422, 2017). "Although CCL5/RANTES levels correlate with cardiac injury and heart failure markers and they decrease during TH, they failed to predict early and late mortality." (PMID 35268485, 2022).
nasal polyps (14 papers, 2011 to 2023). "Notably, mRNA expression of CCL4, but not other well-known eosinophil-associated chemokines, such as CCL5, CCL11, and CCL26, was significantly higher in nasal polyps of patients with ECRS than in uncinate tissues of the same patients." (PMID 36555793, 2022). "Recently, CCL4, CCL5, CCL11, and CCL26 expressions were found to be higher in nasal polyps than in uncinate process tissue in the same patients with ECRS." (PMID 36555793, 2022). "The expression of CCL4 and other eosinophilic chemoattractants (CCL5, CCL11, and CCL26) was reported to be increased in nasal polyps compared with that in uncinate process tissues of the same patients with ECRS." (PMID 36555793, 2022). "The eosinophilic chemo-attractants CCL4, CCL5, CCL11, and CCL26 were increased in nasal polyps compared with uncinate process tissues." (PMID 32085629, 2020). "RANTES/CCL5 (regulated on activation, normal T cell expressed and secreted) is a chemoattractant that recruits and activates eosinophils and this was shown to be elevated in nasal polyps of CF patients." (PMID 24885494, 2014). "Notably, CCL4 expression, but not CCL5, CCL11, or CCL26, was found to be significantly increased in nasal polyps from patients with ECRS associated with eosinophil infiltration as well as in BEAS-2B cells co-incubated with eosinophils." (PMID 36555793, 2022).
neuroblastoma (14 papers, 2013 to 2025). Neuroblastoma (NB) is the most common solid, extracranial childhood tumor. "In murine neuroblastoma models, arming adenovirus with the chemokine like CCL5/RANTES and the cytokine IL-15 not only preserved their oncolytic effects but also enhanced the migration and proliferation of the tumor- associated ganglioside GD2 CAR T cells, thereby increasing overall survival." (PMID 34675919, 2021). "In fact, it has been shown that 50 ng/ml CCL5 induces apoptosis in neuroblastoma cells." (PMID 24225433, 2013). "CCL5-armed oncolytic virus and CAR T cell therapy have been successfully used in combination in a mouse model of neuroblastoma (see next section)." (PMID 35205725, 2022). "In experiments utilizing a human neuroblastoma cell line which expressed a low level of CCR5, CCL5 was neuroprotective in the range of 10–500 ng/ml47." (PMID 24658403, 2014). "Evidence on the direct relationship between CCL5 and neuroblastoma is still lacking and requires further study." (PMID 32963529, 2020).
bladder cancer (13 papers, 2015 to 2025). "Moreover, the secretion levels of IFN-β and CCL5 protein were improved in ASNS-deficient bladder cancer cells by using ELISA." (PMID 39964752, 2025). "We suggest that CCL5 expression can be a prognostic and predictive marker for muscle-invasive bladder cancer patients." (PMID 38928033, 2024). "Because normal cells and unirradiated bladder cancer cells secrete very low levels of CCL5, they cannot recruit enough dendritic cells to initiate the immune response." (PMID 39231199, 2024). "CCL5 is believed to promote the proliferation and metastasis of bladder cancer through the JAK2/STAT3 signaling pathway, which might suggest the reliability of finasteride in reducing the occurrence of BCa from the perspective of the immune microenvironment." (PMID 39944628, 2025). "In contrast, asparagine attenuated the expression of IFN-β and CCL5 in bladder cancer cells." (PMID 39964752, 2025). "Notably, the expression levels of IFN-β and CCL5 were higher in bladder cancer cells treated with ASNase." (PMID 39964752, 2025). "Above all, ATM-MT bladder cancer cells are likely to promote the infiltration of cytotoxic cells and Th17 cells into tumor tissues by secreting relatively large amounts of chemokines, such as CCL5, to activate dendritic cells and promote the therapeutic effect of immune checkpoint inhibition." (PMID 32922441, 2020). "Conversely, high levels of other chemokines like CCL5, CCL8, CCL13, and CCL18 have been correlated with improved outcomes in bladder cancer patients." (PMID 39964621, 2025). "Bladder cancer tissues spontaneously expressed high levels of the granulocyte/MDSC-attractant CXCL8 and Treg-attractant CCL22, but only marginal levels of the CTL-attracting chemokines: CCL5, CXCL9 and CXCL10." (PMID 25806105, 2015). "Therefore, the secretion level of CCL5 and CCL21 was measured to verify whether bladder cancer cells could induce the recruitment of DCs after radiotherapy in this study." (PMID 39231199, 2024). "By means of a 34‐cytokine and chemokine immunoassay panel, we revealed that chemokines including CCL3, CCL4, CCL5, CXCL9, and CXCL10, are robust negative correlated with expression of BCAT2 in human and murine bladder cancer cell." (PMID 36642843, 2023).
cerebral malaria (13 papers, 2005 to 2024). A sequestration of Plasmodium falciparum in the brain, which can cause coma and/or seizures. "This is in line with recent studies on post-mortem tissue samples from human patients that demonstrated an association of CCL5 with cerebral malaria." (PMID 29438386, 2018).
Cirrhosis (13 papers, 2013 to 2026). A chronic disorder of the liver in which liver tissue becomes scarred and is partially replaced by regenerative nodules and fibrotic tissue resulting in loss of liver function. "In patients with HBV-related cirrhosis, the serum level of CCL5 showed an opposite trend, suggesting that decreased CCL5 level was associated with more severe hepatic damage or worsening progression." (PMID 31200663, 2019). "It is also possible that in cirrhosis, the level of CCL5/RNATES increases to antagonize 20-HETE, leading to a decrease in GPR75 synthesis." (PMID 39959811, 2024). "Serum levels of PDGF-BB and of RANTES (CCL5) were decreased in patients with cirrhosis compared to healthy controls." (PMID 38015590, 2023). "The increasing serum levels of CCL5 in patients with CHB and HBV-related cirrhosis were significantly associated with disease progression." (PMID 31200663, 2019). "Compared with CHB patients, the serum CCL5 level of HBV-related cirrhosis patients was significantly decreased (4375.79 pg/mL vs. 11,729.47 pg/mL, P < 0.001)." (PMID 31200663, 2019). "A previous study found that the ligand CCL5 promotes steatosis, inflammation, and early cirrhosis." (PMID 36221095, 2022). "In tissue slices of CHB patients, CCL5 was distributed throughout the cytoplasm near the nucleus, while there was not CCL5-positive signals that were observed in destroyed hepatocytes and the fibrous bands of cirrhosis liver slices." (PMID 31200663, 2019). "Moreover, patients with cirrhosis show marked up-regulation of Ccl5 mRNA." (PMID 23700488, 2013). "Elevated serum CCL5 in CHB- and HBV-related cirrhosis correlates with disease severity, supporting its utility as a biomarker for immune status assessment in CHB." (PMID 41258710, 2026). "The interaction between CCL5 and CCR5 significantly influences macrophage numbers from the state of hepatitis to cirrhosis." (PMID 36221095, 2022). "ROC analysis revealed that the serum levels of CCL5, HA and MIP-1β were effective in distinguishing patients with cirrhosis from patients with CHB, especially for CCL5." (PMID 31200663, 2019). "The results indicated that the serum CCL5 level was dramatically increased in CHB patients with progressive severity from mild to moderate-to-severe stage, but in patients with HBV-related cirrhosis, the opposite trend was observed." (PMID 31200663, 2019). "We observed that only CCL5, MIP-1β, and HA among 23 candidate factors showed significant differences between patients with CHB and HBV-related cirrhosis." (PMID 31200663, 2019). "The serum levels of CCL5, HA and MIP-1β were effective in distinguishing patients with cirrhosis from CHB, and among these factors, CCL5 was the most reliable marker." (PMID 31200663, 2019). "Consistent with the expression of CCL5, the MIP-1β levels in the serum of cirrhosis patients were slightly lower than that of patients with CHB (49.30 pg/mL vs. 75.77 pg/mL, P < 0.05)." (PMID 31200663, 2019). "The CCL5 expression level in liver tissue, according to immunochemistry (ICH) analysis, was decreased in the fibrotic liver tissue of cirrhosis patients compared to that of CHB patients." (PMID 31200663, 2019). "Excluding CCL-11, higher levels of chemokines CCL-3, CCL-4, CCL-5, CXCL-8, and CXCL-10 were observed in compensated cirrhosis patients compared to fibrotic and decompensated cirrhosis patients." (PMID 29977152, 2018). "In cases of HCC associated with MASLD-related cirrhosis, patients exhibited higher levels of fecal calprotectin and plasma levels of IL-8, IL-13, CCL3, CCL4, and CCL5 compared to those with MASLD-induced cirrhosis without HCC." (PMID 39451600, 2024). "ROC analysis demonstrated that CCL5 was the most accurate predictor of hepatic injury within CHB patients, and the most reliable indicator of deterioration in patients within HBV-related cirrhosis patients was HA." (PMID 31200663, 2019).
Cirrhosis (continued). "The serum levels of CCL5, HA and MIP-1β maybe used to distinguish cirrhosis from CHB patients, moreover, CCL5 was the most reliable marker." (PMID 31200663, 2019).
lung adenocarcinoma (13 papers, 2010 to 2025). A carcinoma that arises from the lung and is characterized by the presence of malignant glandular epithelial cells. "This is consistent with a recent study showing that CD8 expression in lung adenocarcinoma is positively correlated with CCL5 and CXCL10 expression." (PMID 38062129, 2024). "Knockdown of glycogen branching enzyme (GBE1) downstream of HIF1 in lung adenocarcinoma led to an increase in CCL5 expression and recruited more cytotoxic CD8+ T lymphocytes to contribute to tumor regression." (PMID 33312950, 2020). "CCL5 activates CCR1, -3 and -5, and CCL5 expression by tumour cells in patients with stage I lung adenocarcinoma has been associated with improved survival." (PMID 20429924, 2010). "The analysis revealed that CCL5 expression is positively correlated with CD8A expression in three cancer types (breast invasive carcinoma, lung adenocarcinoma, and colon adenocarcinoma)." (PMID 36352411, 2022).
non-small cell lung carcinoma (13 papers, 2015 to 2025). A group of at least three distinct histological types of lung cancer, including non-small cell squamous cell carcinoma, adenocarcinoma, and large cell carcinoma. "Intratumoural expression of anti-tumoural chemokines such as CXCL9, CXCL10 and CCL5 were reported in patients undergoing chemotherapy for multiple cancer types such as melanoma, non-small cell lung cancer (NSCLC) and BC." (PMID 40852716, 2025). "For instance, miR-147a can suppress CCL5 expression in non-small cell lung cancer, and regulating CCL5 indirectly using this method had been found to significantly inhibit mouse xenograft tumor growth and metastasis." (PMID 39227943, 2024). "IGF2BPs, as functional downstream modulators of circNDUFB2, regulate the secretion of CXCL10, CXCL11, CCL5, and IFNβ in non-small cell lung cancer (NSCLC)." (PMID 36225914, 2022). "After radiotherapy in non-small cell lung cancer, CCL5 is overexpressed and can induce macrophage infiltration, promoting tumor progression." (PMID 29559701, 2018). "We also observed that the enhanced metastatic capacity of NCSLCs induced by CCL5 is associated with elevated EMT in both A2780 and SKOV3 ovarian tumor models and in two non-small cell lung cancer cell lines (A549 and H1650)." (PMID 25788271, 2015). "MiR-147a represses the growth and metastasis of non-small-cell lung cancer via targeting CCL5." (PMID 35562348, 2022).
pancreatic ductal adenocarcinoma (13 papers, 2018 to 2026). An infiltrating adenocarcinoma that arises from the epithelial cells of the pancreas. "For example, Ccl5 was able to recruit Treg cells in pancreatic ductal adenocarcinoma, and this recruitment was impaired by the neutralization of Ccl5." (PMID 40282557, 2025). "Cancer-FOXP3 directly activates CCL5 to recruit FOXP3+ Treg cells in pancreatic ductal adenocarcinoma." (PMID 31221150, 2019). "Pancreatic ductal adenocarcinoma secretes CCL5 to recruit CCR5+ Treg cells and blocking CCL5 expression could improve anti-tumor immunity." (PMID 35359918, 2022). "It has been reported that the upregulation of CCL5 may promote immune evasion through recruiting Treg cells into tumor lesion and anti-PD-L1 treatment could enhance CCL5-mediated anti-tumor effects in pancreatic ductal adenocarcinoma." (PMID 34938730, 2021). "CCL5 is the most relevant chemokine in terms of the spatial distribution of intratumoral CD8+ T cells in pancreatic ductal adenocarcinoma, it is not elucidated in TNBC." (PMID 40475010, 2025). "Some chemokines, such as CCL5 (RANTES), CXCL10 and CCL2 induced by TNFα, also have been reported to locally recruit both CAR T cells and endogenous T cells when combined with adenoviral OV and mesothelin-redirected CAR T cells in pancreatic ductal adenocarcinoma model." (PMID 36353540, 2022).